BRCA1 (BRCA1 DNA repair associated)
Diseases named in the same sentence as BRCA1 in open-access papers (continued):
Sharing a sentence is not in itself a finding about the gene and the disease.
prostate carcinoma (continued). "Practically, IHC staining of prostate cancer tissues in our center and qRT-PCR analysis of prostate cell lines also showed a close correlation between LMNB1 and BRCA1 expression." (PMID 35241075, 2022). "In the joint analysis of BRCA1 and BRCA2 carriers, men in the top PRSPC quartile had a prostate cancer odds ratio of 3.35 (95% CI = 2.06 to 5.42) compared with men in the lowest quartile (available online)." (PMID 34320204, 2022). "One patient, where a BRCA1 PV/LPV was missed on tumor testing, had a family history of prostate cancer in a second-degree relative." (PMID 35326583, 2022). "Taken together, analyses identified a new mechanism for IGF1R and AR stimulation of prostate cancer, and further support the relevance of targeting AR and IGF1R in this type of tumors with BRCA1 serving as a marker for defining the target activity." (PMID 35432218, 2022). "After quality control, the analyses included 483 BRCA1 (33 breast and 70 prostate cancer cases) and 1318 BRCA2 (244 breast and 141 prostate cancer cases) carriers of European ancestry (available online)." (PMID 34320204, 2022). "PARP inhibitors (PARPi) leverage this synthetic lethality and are US FDA approved to treat germline BRCA1 or BRCA2-mutant breast, ovarian, pancreatic, and prostate cancers." (PMID 34572800, 2021). "Several TFs have been identified for regulating RRM2 transcription in different cancers, such as E2F1 in CRC, BRCA1 and E2F1 in glioblastoma, HPVE7 in cervical cancer, and FOXM1 in prostate cancer, and etc.." (PMID 34234118, 2021). "The results from our study show that breast and prostate cancer are the most common type of cancers diagnosed, particularly in BRCA2 carriers, despite the larger proportion of BRCA1 carriers in our study cohort." (PMID 34575694, 2021). "This is important as studies have shown that prostate cancer patients with certain errors in their genes, such as BRCA2 or BRCA1, are more likely to have worse disease and poorer outcome." (PMID 34830851, 2021). "Of all cancers diagnosed, BC was the most common (N = 26, 57.7%; 3 BRCA1 and 23 BRCA2; P < 0.001), followed by prostate cancer (N = 7, 15.6%; 3 BRCA1 and 4 BRCA2)." (PMID 34575694, 2021). "The entire coding regions and intron/exon boundaries of BRCA1 and BRCA2 genes have been analyzed by next generation sequencing (NGS) in a total of 30 familial prostate cancer patients." (PMID 34242281, 2021). "The hereditary cancer working group from SEOM recommends prostate cancer screening with annual serum PSA measurements in male BRCA2 carriers starting at age 40, while this screening approach can also be offered to BRCA1 carriers." (PMID 32655641, 2020). "For example, AR, EGFR, DDR2 and MAP2K2 were connected with mtDNA genes in prostate cancer, and TMPRSS2, NF1, PIK3CA, BRCA1 and TOP1 were the top neighbors of mtDNA genes in multiple cancer types." (PMID 32024997, 2020). "Differentiation is made between BRCA1 and BRCA2 carriers based on the higher penetrance of prostate cancer in male BRCA2 carriers." (PMID 32655641, 2020). "A transcriptional role for MYCN in upregulating the DDR has been given further credence by the recent identification of MYCN binding sites in the promoters of PARP1, PARP2, BRCA1, RMI2, and TOPBP1, albeit in castration resistant prostate cancer." (PMID 32577161, 2020). "Of these, BRCA2, BRCA1, and ATM account for 19.3% overall and they were substantially more frequent in mCRPC compared to those in primary prostate cancers." (PMID 31357527, 2019).
prostate carcinoma (continued). "Among the 421 male participants, 2.9% of BRCA1 PV carriers and 6.2% of BRCA2 PV carriers were diagnosed with prostate cancer at inclusion (mean age at diagnosis for BRCA1: 61.5, range 48–71 and 64.1, range 50–78 for BRCA2)." (PMID 30430080, 2018). "Although the contribution of the homologous recombination mediators BRCA1 and BRCA2 to prostate cancer has been previously investigated, this is the first study to address the importance of RAD51 genetics in the occurrence of sporadic prostate cancer." (PMID 26433958, 2015). "The BRCA1 and BRCA2 genes, whose best known function is concerned with the DNA damage response, have been reported to contribute to prostate cancer, although to different extents." (PMID 26433958, 2015). "For example, gene BRCA1 with degree 129 is strongly related to prostate cancer, and articulation hub of gene NCOA4 with only degree 8 is also the annotated cancer gene in prostate cancer." (PMID 22577352, 2012). "In the same prostate cancer cell line model, a new HDAC inhibitor, H6CAHA, suppressed the expression of BRCA1 mRNA, and when used in combination with γ-radiation, prevented the growth of tumor xenografts." (PMID 21854619, 2011). "E2F1 protein levels were depleted with valproic acid exposure in prostate cancer cell lines and valproic acid reduced E2F1 binding to the BRCA1 promoter, thus providing insight into a mechanism for the down regulation of the BRCA1 gene by HDAC inhibition." (PMID 21854619, 2011). "Here, we tested the effect of I3C on BRCA1 and BRCA2 expression in breast and prostate cancer cells." (PMID 16434996, 2006). "Our findings indicate that genistein upregulates BRCA1 and BRCA2 expression in breast and prostate cancer cell lines." (PMID 16434996, 2006). "We reanalyzed the data from 11 300 prostate cancer patients and found a higher proportion of aggressive prostate cancer in BRCA1 carriers than in noncarriers." (PMID 41423785, 2026). "The proportion of aggressive prostate cancer was higher in BRCA1 carriers (86.7%) than in noncarriers (61.1%) (odds ratio = 4.87; 95% confidence interval = 1.05 to 22.60)." (PMID 41423785, 2026). "Consequently, detecting CNV deletions of exon 22 in BRCA1 and exon 27 in BRCA2 is critical for guiding therapeutic strategies for advanced prostate cancer." (PMID 40725150, 2025). "The contribution of BRCA1 mutations to familial prostate cancer is not as strong as that seen for BRCA2, although BRCA1 mutations have been associated with some populations with a family history of prostate cancer." (PMID 40433050, 2025). "Notably, ROC curve analysis demonstrated 100% sensitivity and specificity for BRCA1/2 CNV detection, highlighting the technique’s potential for clinical application in advanced prostate cancer diagnostics." (PMID 40725150, 2025). "Compared with wild-type (WT) tumors, significantly more adaptive immune response cells, especially tumor-infiltrating lymphocytes (TILs), are enriched in BRCA1/2 mutant TNBC, as well as prostate cancer and pancreatic cancer with BRCA2, PALB2, or ATM germline mutations." (PMID 40830526, 2025). "BRCA1 and BRCA2 are two tumor suppressor genes that are involved in DNA repair, and alterations in BRCA1/2 increase the likelihood of epithelial malignancies, including prostate cancer." (PMID 39272896, 2024). "Specifically, AR antagonists demonstrate contextual synthetic lethality with PARPi by modulating the expression of key HR proteins such as BRCA1/2 and RAD51, and potentially enhance the vulnerability of prostate cancer cells on alternative DNA repair mechanisms, such as PARP-mediated repair." (PMID 37812088, 2023). "Germline mutations and somatic mutations in BRCA1 and BRCA2 gene mutations account for approximately 6–7% each in prostate cancer; however, they do not strongly affect PSA values." (PMID 37848957, 2023). "For example, laboratory-developed panels may be designed for analyzing only BRCA1/BRCA2 and the other HRR genes clinically relevant in prostate cancer." (PMID 37240284, 2023).
prostate carcinoma (continued). "The combination of vorinostat with the PARP inhibitor veliparib also revealed synergistic effects on prostate cancer cell viability (in particular, on the viability of BRCA1-mutant DU145 cells), apoptosis induction, DNA damage production, and BRCA1 suppression." (PMID 35582529, 2022). "In a study of 6500 patients with BRCA1 and BRCA2 PVs, c.756-c 1000 and c.7914þ regions in BRCA2 were reported as negative biomarkers for high risk of Gleason 8b prostate cancer." (PMID 36010882, 2022). "The past decade has seen several therapeutic breakthroughs for prostate cancer, including the approval of two PARP inhibitors—rucaparib and olaparib—for mCRPC patients harboring germline or somatic aberrations in DDR genes such as BRCA1 and BRCA2." (PMID 35159068, 2022). "PROREPAIR-B is an ongoing prospective study to evaluate the outcomes of patients with metastatic castrate-resistant prostate cancer with and without germline ATM/BRCA1/BRCA2/PALB2 mutations." (PMID 35732815, 2022). "Prostate cancer is dominated by BRCA2 prevalence at 9.6%, while BRCA1 has only 1.2%." (PMID 34979999, 2022). "Mechanistically, exosomal miR-146a-5p has been shown to confer prostate cancer cells metastatic abilities through EGFR/ERK pathway, downregulate BRCA1 in triple negative sporadic BCs and play a central role within the STAT/IFN signaling axis to create an immunosuppressive microenvironment." (PMID 36293478, 2022). "In addition, the alterations of gene expression are also considered to be related to the development of prostate cancer, such as HOXB13, BRCA1, BRCA2, as well as our protagonists HSP90 and HSP70." (PMID 36294924, 2022). "The combination of vorinostat with olaparib synergistically reduced prostate cancer cell viability, induced apoptosis in DU145 and PC3 prostate carcinoma cells, and suppressed DNA repair as well as DNA repair protein expression (BRCA1 and RAD51) in DU145 cells." (PMID 35582529, 2022). "Germline mutations of BRCA1/2 and ATM are associated with worse prognosis in prostate cancer, while to-date, somatic mutations are not shown to be." (PMID 33781305, 2021). "Family history of prostate cancer was seen in 15.4% of PALB2 carriers but in only 1.7% of BRCA1 carriers (p-value = 0.001); there was no significant different between PALB2 and BRCA2 carriers (p-value = 0.594)." (PMID 34439348, 2021). "Germline or somatic mutations in DNA damage repair (DDR) genes, such as BRCA2, CHEK2, ATM, RAD51D, BRCA1, and PALB2, have been described in around 20–25% of advanced prostate cancer patients, which involved in aggressive disease and poor outcomes in these patients." (PMID 33413230, 2021). "BRCA1 and BRCA2 accounted for 2 patients (100%) in 7 prostate cancer patients." (PMID 33649982, 2021). "Importantly, the HRR abnormalities are observed in 31% of advanced prostate cancers and include: BRCA2 (9.8%), CDK12 (5.6%), ATM (5.2%), CHEK2 (1.8%), BRCA1 (1.4%) FANCA (1.3%), and ATR (1.1%)." (PMID 31366128, 2019). "Moreover, aberrations of BRCA2, BRCA1, and ATM were observed in mCRPC at clearly higher frequencies than in primary prostate cancers." (PMID 31366128, 2019). "Although PARPi have not been approved for treating prostate cancer yet, both olaparib and rucaparib have FDA-breakthrough designations for BRCA1/2-mutated mCRPC." (PMID 31404966, 2019). "In conclusion, BRCA1/2 protein expression is not a suitable surrogate maker for BRCA1/2 inactivation in prostate cancer." (PMID 28676659, 2017). "For men who are carriers of a BRCA1 mutation, data from the BCLC, and other studies have shown that there is an approximately four-times relative risk of developing prostate cancer for the under 65 compared with those without the mutation." (PMID 28031937, 2016). "Although germline mutations and LOH in BRCA1 and BRCA2 genes have been detected in mutation carriers, no data currently exist concerning the role of RAD51 in sporadic prostate cancer." (PMID 26433958, 2015).
prostate carcinoma (continued). "In prostate cancer, autoantibody frequency to PARP1/BRCA1/BRCA2 were 2.8% (3/107), 28.0% (30/107) and 4.7% (5/107), 1.9% (2/107), 0.9% (1/107) and 1.9% (2/107) were shown to have autoantibody to PARP1 and BRCA1, PARP1 and BRCA2, or BRCA1 and BRCA2." (PMID 25865228, 2015). "This study analyzed the tumor features and outcomes of 2,019 patients with prostate cancer (18 BRCA1 carriers, 61 BRCA2 carriers, and 1,940 non-carriers)." (PMID 25047061, 2014). "If survival in BRCA1 carriers is atypical, then our observed difference will not be representative of prostate cancer in general." (PMID 18577985, 2008). "Several other cancer types were detected in the 1st–3rd degree relatives of almost all BRCA1, BRCA2 and PALB2 carriers, the most common ones being stomach (in 10 families), lung (9 families), colorectal (6 families), pancreatic (6 families) and prostate cancer (5 families)." (PMID 40009290, 2025). "BRCA1 does not appear to be a significant contributor to prostate cancer progression." (PMID 40046829, 2025). "Nonetheless, this study represents a meaningful advancement towards the clinical translation of ddPCR-based BRCA1/2 CNV detection, and these integrated tools may ultimately support the development of clinically actionable CNV biomarkers in prostate cancer and other malignancies." (PMID 40725150, 2025). "However, in Ashkenazi men with prostate cancer, the prevalence of BRCA1 and/or BRCA2 is not well defined." (PMID 36612302, 2023). "However, PARP inhibitors are not effective in all patients with BRCA1/2 mutant prostate cancer, and the inactivation of DDR genes elicits genomic instability, leading to alterations in multiple genes and eventually to drug resistance." (PMID 37174127, 2023). "However, olaparib (Lynparza®) is not effective in all BRCA1/2 mutant prostate cancer patients and inactivation of DDR genes elicits genomic instability, leading to alterations in multiple genes, which eventually leads to drug resistance." (PMID 37174127, 2023). "In addition, there was a negative correlation between IGF1R and BRCA1 expression levels in AR-negative prostate cancer cells whereas in cells with an active AR there was a positive correlation." (PMID 35432218, 2022). "Reversion mutations that restore BRCA1/2 function have been shown to be responsible for resistance to platinum-based chemotherapy and PARP inhibitors, however there is no information on the sequential use of these agents in prostate cancer." (PMID 32171277, 2020). "Towards achieving this goal, we identified an unexpected role for activation of cofactor of BRCA1 (COBRA1), a protein traditionally known to be involved in transcription pausing as yet another mechanism potentially contributing to progression to aggressive prostate cancer." (PMID 30036938, 2018). "The experiences of male BRCA1/2 carriers who have prostate cancer are not reported." (PMID 28812325, 2017). "To test this hypothesis in human prostate cancers, we performed unsupervised hierarchical clustering of transcriptional data from 11 SPOP mutant and 53 SPOP wild-type tumors, based on the transcriptional signature of BRCA1 inactivation (MSigDB: M2748)." (PMID 26374986, 2015). "MRE11A, which has been suggested to be correlated with the progression and poor survival of prostate cancer, interacts with ATM, NBN, and BRCA1.12,15 Therefore, the loss-of-function in BRCA1 may affect MRE11A, affecting its progression rather than its development." (PMID 41423785, 2026). "Similarly, we found a significantly increased risk for prostate cancer in male relatives of BRCA2 carriers (RR = 4.86; P = 0.001), but a non-significant risk in male relatives of BRCA1 carriers (RR = 2.19; P = 0.241); our finding is in agreement with previous studies." (PMID 36861435, 2023).
prostate carcinoma (continued). "Another UK Biobank based study reported similar results on the same cancers with minor differences in the monogenic gene selection (BRCA1 and CHEK2 were not used for prostate cancer) and PRS was divided by population tertiles." (PMID 40016794, 2025). "Patients with prostate cancer who did not respond to prostate‐specific membrane antigen‐targeted alpha‐radiation therapy had their BRCA1 and BRCA2 genes removed, and multiple BRCA1 variations had been found." (PMID 37808268, 2023). "Instead, a prostate cancer cluster region (PCCR) was identified in BRCA2 gene from c.7914 to 3′, but no PCCR was established in BRCA1." (PMID 38203374, 2023). "In a meta-analysis, the pooled relative risks (RRs) for prostate cancer were 4.35 and 1.18 for non-Ashkenazi European ancestry BRCA2 and BRCA1 GPV carriers, respectively." (PMID 35806485, 2022). "Overall, PVs in both BRCA1/2 and in non-BRCA genes grouped together are slightly more frequent at the somatic level in pancreatic cancer, whereas in prostate cancer, somatic PVs are twice as many as germline PVs." (PMID 35563100, 2022). "MRI has generally been shown to have superior sensitivity for clinically significant sporadic prostate cancer when compared to TRUS biopsies, but no data is available for carriers of BRCA1/2." (PMID 34298749, 2021). "A total of 2,932 men with no history of prostate cancer were categorized into 919 germline BRCA1 carriers, 902 germline BRCA2 carriers, 479 germline BRCA2 non-carriers and 709 germline BRCA1 non-carriers." (PMID 34884434, 2021). "For example, Gleason score is needed to fully assess BRCA1/2 testing criteria; however, this was not systematically included on the TRF and thus unavailable for many prostate cancer patients in this study." (PMID 31406321, 2020). "To learn about the statuses of BRCA1 and BRCA2 in prostate cancer and non-cancerous cells, we assessed their protein levels." (PMID 30012171, 2018). "However, due to differences in cohort selection and DNA sequencing approaches, the burden of PVs in non-BRCA1/2 DDR genes shared by pancreatic and prostate cancers is not completely defined." (PMID 35563100, 2022). "Evidence for functional interactions between BRCA1 and androgens was suggested by experiments showing differential regulation of the IGF1R gene by BRCA1 in androgen receptor (AR) positive, as compared to AR negative, prostate cancer cells." (PMID 35432218, 2022). "In addition, an inverse correlation between BRCA1 and IGF1R levels was seen in androgen receptor (AR) negative prostate cancer cell lines." (PMID 28706506, 2017). "In the genes of the MEmagenta module, we found that the known genes closely related to cancer stemness in non-prostate cancer, such as BRCA1, EZH2, FOXM1, CDC20, and CDCA8, were all clustered in this module, indicating these genes were also closely related to the stemness of prostate cancer cells." (PMID 33985534, 2021).